SYNE1 (spectrin repeat containing nuclear envelope protein 1)
Description:
Multi-isomeric modular protein which forms a linking network between organelles and the actin cytoskeleton to maintain the subcellular spatial organization. As a component of the LINC (LInker of Nucleoskeleton and Cytoskeleton) complex involved in the connection between the nuclear lamina and the cytoskeleton. The nucleocytoplasmic interactions established by the LINC complex play an important role in the transmission of mechanical forces across the nuclear envelope and in nuclear movement and positioning. May be involved in nucleus-centrosome attachment and nuclear migration in neural progenitors implicating LINC complex association with SUN1/2 and probably association with cytoplasmic dynein-dynactin motor complexes; SYNE1 and SYNE2 may act redundantly. Required for centrosome migration to the apical cell surface during early ciliogenesis. May be involved in nuclear remodeling during sperm head formation in spermatogenesis; a probable SUN3:SYNE1/KASH1 LINC complex may tether spermatid nuclei to posterior cytoskeletal structures such as the manchette.
Synonyms: KASH1; C6orf98; KIAA0796; MYNE1; SYNE-1B; 8B; Nesprin-1; enaptin; CPG2; dJ45H2.2; SCAR8; ARCA1; Nesp1; AMC3; AMCM; EDMD4
Tractability: Small molecule: a structure with a bound ligand is known. Antibody: UniProt predicts a signal peptide or a membrane-spanning region. PROTAC: ubiquitination databases record sites on it; its protein half-life has been measured.
Gene: Protein-coding gene on chromosome 6 (152,121,687 to 152,637,801, reverse strand). Ensembl gene ENSG00000131018.
Subcellular location: Nucleus outer membrane; Nucleus; Nucleus envelope; Cytoplasm, cytoskeleton; Cytoplasm, myofibril, sarcomere; Golgi apparatus (Isoform GSRP-56)
Subcellular location (Human Protein Atlas): Nuclear membrane; Nucleoplasm
Pathways (Reactome):
Reproduction: Meiotic synapsis
Gene Ontology:
Molecular function: actin binding; cytoskeleton-nuclear membrane anchor activity; enzyme binding; lamin binding; protein binding; RNA binding; actin filament binding; protein homodimerization activity; identical protein binding
Biological process: Golgi organization; muscle cell differentiation; nuclear matrix anchoring at nuclear membrane; centrosome localization; nuclear migration; nucleus organization; regulation of cilium assembly
Cellular component: cytoplasm; Golgi apparatus; meiotic nuclear membrane microtubule tethering complex; membrane; nuclear envelope; nuclear membrane; nucleolus; nucleoplasm; nucleus; P-body; postsynaptic membrane; sarcomere; sarcoplasmic reticulum; cytoskeleton; nuclear outer membrane
Genetic constraint (gnomAD): Loss-of-function variants: 594 observed, 1,126.6 expected, observed/expected ratio (o/e) 0.53, 90% interval 0.49 to 0.56. The upper end of that interval is the gene's LOEUF score, 0.56, which puts it in group 2 of 6, group 1 being the genes least tolerant of losing a copy. Missense variants: 9,826 observed, 10,771 expected, observed/expected ratio (o/e) 0.91, 90% interval 0.9 to 0.93. Synonymous variants: 3,810 observed, 3,988.3 expected, observed/expected ratio (o/e) 0.96, 90% interval 0.93 to 0.98.
Gene-disease validity (ClinGen):
ClinGen rates the evidence that SYNE1 causes each of these diseases.
autosomal recessive ataxia, Beauce type (autosomal recessive): Definitive. A rare disorder characterized by a slowly progressive pure cerebellar ataxia associated with dysarthria.
arthrogryposis multiplex congenita 3, myogenic type (autosomal recessive): Moderate.
Homologues: Orthologues: chimpanzee SYNE1 (99% identical), macaque SYNE1 (98% identical), dog SYNE1 (92% identical), rabbit SYNE1 (89% identical), rat Syne1 (85% identical), mouse Syne1 (85% identical), tropical clawed frog syne1 (67% identical), zebrafish syne1a (49% identical), guinea pig Syne1 (10% identical). Paralogues in human: SYNE2 (24% identical), MACF1 (13% identical), DST (12% identical), PLEC (7% identical), SPTBN2 (6% identical), SPTBN1 (6% identical), SPTB (6% identical), SPTBN4 (6% identical), SPTBN5 (6% identical), DMD (6% identical), UTRN (6% identical), PKHD1L1 (4% identical), and 24 more.
Diseases named in the same sentence as SYNE1 in open-access papers:
SYNE1 is named in the same sentence as 153 diseases in open-access papers, as found by Europe PMC text mining. Sharing a sentence is not in itself a finding about the gene and the disease. The quoted sentences say what the papers report.
Ataxia (30 papers, 2014 to 2025). Ataxia refers to impaired coordination of voluntary muscle movement. "The sSNV 6-152631823-C-T, one of the top-scoring SilVA variants,is located on the gene SYNE1, which has been associated with spinocerebellar ataxia.This pathway was found to be enriched in 66 genes." (PMID 38259032, 2024). "We describe a case of severe adult-onset progressive tremulous cerebellar ataxia with pyramidal signs associated with a rare homozygous truncating pathogenic variant in the SYNE1 gene (p.Arg5371*)." (PMID 37388713, 2023). "In this report, we describe an Italian patient with adult-onset tremor, cerebellar ataxia, and pyramidal signs associated with a rare homozygous truncating mutation in the SYNE1 gene." (PMID 37388713, 2023). "In humans, pathogenic SYNE1 variants have been initially reported to cause a slowly progressive, relatively pure cerebellar ataxia (spinocerebellar ataxia, autosomal-recessive 8; SCAR8), mainly observed in Quebec, Canada." (PMID 37388713, 2023). "In the present study, 9.3% (5/54) of ataxia patients had biallelic truncating variants in SYNE1, demonstrating that SCAR8 is also a common subtype of recessive ataxia in China." (PMID 34663476, 2021). "In conclusion, this paper demonstrates the detailed neurological assessment of the first Hungarian SYNE1 ataxia patients with novel pathogenic mutations." (PMID 33526008, 2021). "Father (III:4) and aunt (III:3) had the same variants in genes: ABCG8, BIN1, SCN2B, and SYNE1 (related to Emery-Dreifuss muscular dystrophy with cardiomyopathy, cardiac conduction defects, and cerebellar ataxia)." (PMID 33829027, 2021). "Defects in SYNE1 are associated with adult-onset, slowly progressive, relatively pure cerebellar ataxia with only a few extracerebellar symptoms (SCAR8), and almost all reported variants that cause this phenotype are protein truncations." (PMID 34663476, 2021). "The Nesprins are encoded by genes called synaptic nuclear envelope-1 and -2 (SYNE-1 and -2), which contain ≥80 disease-related variants that cause cerebellar ataxias or muscular dystrophies." (PMID 32040548, 2020). "Here, we screened SYNE1 mutations among a cohort of 126 unrelated index patients with unexplained autosomal recessive or sporadic ataxia in China, by whole-exome sequencing or targeted panel sequencing." (PMID 30619065, 2018). "Except for SYNE1 ataxia, SYNE1 variants have been found to cause other Mendelian disease, including Emery-Dreifuss muscular dystrophy 4 (EDMD4), and arthrogryposis multiplex congenital (AMC)." (PMID 30619065, 2018). "It is for this reason that we included SYNE1 in our panel leading to the identification of two variants in a patient who presented ataxia and CPEO in adulthood with mitochondrial aggregates and multiple deletions of mtDNA in muscle." (PMID 29625556, 2018). "In this study, we identified 2 unrelated index ataxia patients with novel SYNE1 truncating variants, accounting for 1.6% (2/126) in this Chinese cohort of recessive and sporadic ataxia patients." (PMID 30619065, 2018). "Gradually, a growing number of ataxia patients with a wide range of extra-cerebellar neurological and non-neurological dysfunctions, have been found with pathogenic recessive SYNE1 mutation, in different cohorts of ataxia patients from Europe." (PMID 30619065, 2018). "In conclusion, we reported the first two Chinese SYNE1 ataxia families caused by novel SYNE1 mutations, accompanied by motor neuron impairment, mental retardation, with or without arthrogryposis." (PMID 30619065, 2018). "Coincidentally, the variants of the only two SYNE1 ataxia patients with arthrogryposis, were all located in a very close region (SR61-SR63) of SYNE1 protein." (PMID 30619065, 2018). "SYNE1 alterations are linked to cerebellar ataxia and have been associated with lung, ovarian, and CRCs." (PMID 28769798, 2017).
Ataxia (continued). "On another hand, mutations in SYNE1 found in Japanese patients correlated with SpinoCerebellar ataxia, Autosomal Recessive type 8 (SCAR8) associated with motor neuron disease." (PMID 28854936, 2017). "Here, we expand the ethnic and genetic diversity of SYNE1 associated cerebellar ataxia, an important gene to be screened in recessive and sporadic cases." (PMID 27178001, 2016). "With the first British and Sri Lankan cases detected in this study, we further extend the ethnic diversity underlying SYNE1 associated cerebellar ataxia." (PMID 27178001, 2016). "More recently families from Japan and Turkey with homozygous truncating SYNE1 mutations have been associated with a motor neuron phenotype in addition to cerebellar ataxia." (PMID 27178001, 2016). "Even though based on very low numbers of patients, these observations are mirrored via the other recent reports in the literature with SYNE1 associated cerebellar ataxia being relatively mild and slowly progressive." (PMID 27178001, 2016). "We identified in the present cohort a patient carrying a novel mutation, c.3715G > T; p.Glu1239*, in the SYNE1 gene, thereby reporting the first Algerian patient with a genetically confirmed recessive ataxia SCAR8." (PMID 26068213, 2015). "Inherited recessive cerebellar ataxia has been attributed to mutations in SYNE1, a component of the linker of nucleoskeleton and cytoskeleton (LINC) complex." (PMID 26035387, 2015). "Mutations in Nesprin-1 and 2 (also called Syne-1 and 2) are associated with numerous diseases including autism, cerebellar ataxia, cancer, and Emery-Dreifuss muscular dystrophy." (PMID 25010424, 2014). "In muscle, SYNE1 is involved in anchoring specialized myonuclei underneath the neuromuscular junctions, and SYNE1 mutations may cause ataxia." (PMID 38742190, 2024). "Among the 158 upregulated genes, we found that Syne1 was associated with cerebellar ataxia." (PMID 40276214, 2024). "Syne1 mutations have been shown to play important roles in cerebellar ataxia." (PMID 36690791, 2023). "SYNE1 mutations were originally associated with pure cerebellar ataxia." (PMID 34946884, 2021). "It is highly likely that further genetic, epigenetic and environmental modifiers are contributing to the phenotypic variability and it is recommended therefore that SYNE1 mutations be considered also in the aetiology of complex as well as pure recessive ataxia." (PMID 27178001, 2016). "SYNE1 was originally discovered in 2007 as the causal gene underlying autosomal recessive spinocerebellar ataxia 1, a disease clinically thought to manifest with mainly pure cerebellar ataxia." (PMID 27178001, 2016). "In addition, SYNE1 deficiency is one of the most common genetic causes of cerebellar ataxia, which may be of interest given the reported evidence of the cerebellum involvement in the pathophysiology of ADHD." (PMID 31652596, 2019). "However, unpublished results suggested that patients presenting with ataxia associated with SYNE1 mutations may have a secondary mitochondrial dysfunction." (PMID 29625556, 2018). "In humans, numerous mutations in the LINC complex gene spectrin repeat containing nuclear envelope protein 1 (SYNE1) have been identified in cerebellar ataxia." (PMID 39519078, 2024). "This contrasts the initial view on SYNE1-related ataxia as a relatively benign, slowly progressive condition, with important implications for clinic-genetic counselling." (PMID 37388713, 2023). "Our results raise the possibility that impaired posttranscriptional regulation of SYNE-1 exacerbates the ataxia phenotypes." (PMID 32040548, 2020). "Six of these candidate variants were located in genes related to ataxia phenotype including ATM, GALC, SPTBN2, SYNE1, and TWNK." (PMID 31455392, 2019). "These reported SYNE1 ataxia patients show a strong heterogeneity in clinical features and disease severity, ranging from a pure cerebellar ataxia to a complex multisystem disorder." (PMID 30619065, 2018).
Ataxia (continued). "The differential diagnosis in an adolescent with paroxysmal dyskinesias and ataxia includes a broad range of conditions, such as autosomal recessive cerebellar ataxias (ARCA, e.g., SETX, SYNE1 mutations), ataxia telangiectasia, organic acidemias, and juvenile-onset mitochondrial epileptic syndromes." (PMID 41568333, 2025). "The patient who has ataxia, pes cavus, dysarthria, impaired cognition, onset at ages 6–40, and motor neuropathy on EMG suggests that it is compatible with “Spinocerebellar ataxia, autosomal recessive 8” caused by homozygous mutation in the SYNE1 gene." (PMID 38587696, 2024). "Patient #40 had a history of spinocerebellar ataxia and moderately sized posterior polar cataracts; WES identified two P variants in gene SYNE1, which has been previously reported in congenital muscular dystrophy, a condition known to be associated with cataracts." (PMID 36980880, 2023). "Till now, only four Japanese and two Korean SYNE1 ataxia families were reported in Eastern Asia population, and no mutation of SYNE1 ataxia has been reported among the Chinese population." (PMID 30619065, 2018). "Disease-causing SYNE1 variants were previously reported in a large clinical spectrum with bi-allelic mutations responsible for SCAR8 phenotype including pure cerebellar atrophy, ataxia and dysarthria, with variable age at onset of symptoms (6–50 years)." (PMID 29625556, 2018). "Due to the large size of SYNE1, the most giant isoform (nesprin-1 giant or enaptin) of which consists of 146 exons, it is hard to screen SYNE1 gene by conventional Sanger sequencing in ataxia patients." (PMID 30619065, 2018). "ARCA1, which is inherited in an autosomal recessive pattern, is associated with SYNE1 mutations and its main clinical features include adult-onset (17–46 years), gait and limb ataxia, dysarthria, dysmetria, mild oculomotor abnormalities, and cerebellar atrophy." (PMID 35648332, 2023). "Until now, no mutation of SYNE1 ataxia has been reported among the Chinese population." (PMID 30619065, 2018). "However, no hot mutation spot was observed in all reported SYNE1 ataxia patients with motor neuron disorders (Supplementary Material_Table S4)." (PMID 30619065, 2018). "Further, we demonstrate that ARSACS (gene: SACS; n = 6, 22.2%), SCAR8 (gene: SYNE1; n = 5, 18.5%), SCAR9 (gene: ADCK3; n = 5, 18.5%) and AOA2 (gene: SETX; n = 4, 14.8%) are the most common recessive ataxia subtypes in the Chinese population." (PMID 34663476, 2021).
Emery-Dreifuss muscular dystrophy (25 papers, 2012 to 2026). Emery-Dreifuss muscular dystrophy (EDMD) is characterized by muscular weakness and atrophy, with early joint contractures and cardiomyopathy. "A defect in nesprin-1 encoded by the SYNE1 gene can cause Emery-Dreifuss muscular dystrophy (EDMD), which is characterized by joint contracture, myasthenia, and cardiac abnormalities." (PMID 34987544, 2021). "Myonuclear clustering is also found in ageing muscles of Emery Dreifuss muscular dystrophy patients and, in mice, genomic deletion of Syne-1 (Nesprin-1 coding gene) results in nuclear clustering associated with decreased exercise ability." (PMID 34831284, 2021). "While mutations in the SYNE1 gene may induce myogenic multiple congenital joint contractures, dilated cardiomyopathy, Emery-Dreifuss muscular dystrophy, and other muscle abnormalities." (PMID 40547219, 2025). "LMNA, in addition to multiple myopathic phenotypes, also causes Charcot-Marie Tooth disease or progeria, and SYNE1 can cause one type of Emery-Dreifuss muscular dystrophy, a dilated cardiomyopathy syndrome, a form of autosomal recessive arthrogryposis, and autosomal recessive spinocerebellar ataxia." (PMID 25353622, 2014). "SYNE1 has been implicated in Emery-Dreifuss muscular dystrophy (muscle wasting and weakness)." (PMID 25211016, 2014). "Furthermore, heterozygous missense mutations in SYNE1 have been identified in dominant muscular dystrophy and two unrelated probands with Emery-Dreifuss muscular dystrophy (MIM# 612998) where only the exons contributing to the muscle specific isoform of SYNE1 were investigated." (PMID 27178001, 2016). "Mutations in SYNE1 and SYNE2, encoding nesprin 1 and 2, respectively, cause Emery-Dreifuss muscular dystrophy." (PMID 36120560, 2022). "Other structural proteins (e.g., SYNE1 and SYNE2) also cause an Emery-Dreifuss muscular dystrophy phenotype (EDMD type 3)." (PMID 29750601, 2018). "Beyond psychiatric implications, Syne1 has been linked to a range of genetic disorders, such as autosomal recessive cerebellar ataxia type 1 (ARCA1), Emery-Dreifuss muscular dystrophy, and myogenic arthrogryposis, indicating its crucial role in neurological disorders." (PMID 39304885, 2024). "In agreement with this pathogenetic hypothesis, Erk 1/2 activation has been demonstrated in the presence of pathogenetic LMNA and SYNE1 mutations, and altered positioning of muscle nuclei has been demonstrated in LMNA, SYNE1 and SUN1-linked Emery-Dreifuss muscular dystrophy with cardiomyopathy." (PMID 30130999, 2018). "Emery-Dreifuss muscular dystrophy (EDMD) was initially linked to mutations in the EMD gene, which encodes the INM protein emerin, but can also be caused by mutations in LMNA and NE genes SYNE1, SYNE2 and TMEM43." (PMID 24490688, 2014).
colon cancer (18 papers, 1990 to 2024). "SYNE1 expressed in skeletal and smooth muscle and localizes to the nuclear membrane, but a lot of studies reported that missense mutations, silent mutations, nonsense mutations, and frameshift deletions on SYNE1 were observed in colon cancer, stomach cancer, breast cancer and so forth." (PMID 27835590, 2016). "We analyzed the changes in SLC7A7 and gene mutations, acquisitions, and deletions in colon cancer, the difference in APC, TTN, KRAS, SYNE1, RYR2, and LRP1 mutations was statistically significant." (PMID 39730571, 2024). "SYNE1 was implicated in many cancers and gene expression profiles analysis in TCGA displayed that SYNE1 was downregulated in 18 cancer types, including NSCLC, breast cancer and colon cancer, etc, compared with normal tissues." (PMID 30956756, 2019).